SIRT3 (sirtuin 3)
Diseases named in the same sentence as SIRT3 in open-access papers (continued):
Sharing a sentence is not in itself a finding about the gene and the disease.
breast cancer (continued). "Although some other sirtuin molecules like SIRT7 have impacts on breast cancer, little is known about the contribution of SIRT3." (PMID 27686535, 2017). "Previous studies reported that OA functioned as a Sirt3 activator in human breast cancer cells and as an acute Sirt3 activator in an in vitro model of cardiac myocyte insulin resistance." (PMID 29234485, 2017). "SIRT3 has been noted extensively for its role in different types of cancer such as oral cancer, breast cancer, esophageal cancer, lung cancer, gastric cancer, and hepatocellular carcinoma and also in other diseases such as AD, HD, ALS, and AHL." (PMID 27686535, 2017). "SIRT3 has been described as a tumor suppressor in breast cancer, hepatocellular carcinoma, B cell malignancies and leukemia, and metastatic ovarian cancer." (PMID 28704962, 2017). "A form of human cancer known as luminal B breast cancer is suspected to have certain linkage with the inefficiency of SIRT3." (PMID 27686535, 2017). "To validate the relevance of the SIRT3/FOXO3a/SOD2 axis of the UPRmt to human disease we analyzed a collection of primary breast cancer samples from patients." (PMID 28470001, 2017). "A study of the Tam‐resistant human breast cancer cell line (MTR‐3) revealed significant upregulation of SIRT3 at both the mRNA and protein levels." (PMID 27686535, 2017). "Sirt3 was further found to play a role in the UPR cascade of breast cancer cells, modulating the antioxidant machinery." (PMID 27232755, 2016). "Aberrant expression of SIRT3 is detected in breast cancer, oral cancer, squamous cell carcinoma, melanoma, and hepatocellular carcinoma." (PMID 27367026, 2016). "In this regard, SIRT3 loss increases cellular ROS levels, contributing to genomic and mitochondrial DNA instability, and SIRT3 KO mice develop estrogen receptor and progesterone receptor-positive mammary tumors." (PMID 27916001, 2016). "To validate the role of Sirt3 in regulation of autophagy and apoptosis under stressful condition, we silenced the Sirt3 expression in the human breast cancer cells, following by hypoxia treatment, and the measured autophagic and apoptotic activities." (PMID 27270321, 2016). "SIRT3 altered sensitivity of breast cancer cells to tamoxifen (Tam), a commonly used anti-estrogen agent." (PMID 27367026, 2016). "The regulatory role of Sirt3 in autophagy and apoptosis was also observed in human breast cancer cells." (PMID 27270321, 2016). "Silencing of Sirt3 expression decreased autophagy in human breast cancer cells exposed to hypoxia, as indicated by an increase in p62 protein level, and decreases in LC3 and Atg5–12 proteins." (PMID 27270321, 2016). "Inhibition of Sirt3 in breast cancer cells undergoing proteotoxic stress severely impairs the mitochondrial network and results in cellular death." (PMID 27232755, 2016). "Consistent with the results obtained with glioma cells, silencing of Sirt3 expression facilitated the down-regulation of Mcl-1 and survivin protein, and promoted the induction of apoptosis in human breast cancer cells under hypoxia." (PMID 27270321, 2016). "Another possibility is via effects of SIRT3 on Lon protease since both proteins co-precipitate in breast cancer cells exposed to oxidative and hypoxic stress and SIRT3 silencing results in hyperacetylation and inactivation of Lon." (PMID 26370974, 2015). "In the present study, we show that OA inhibits glycolysis in breast cancer cells through SIRT3-mediated HIF1α destabilization, which has important implications for treatment of cancers." (PMID 25855962, 2015). "In our previous studies, oroxylin A promoted glycolysis in human breast cancer cells by upregulating SIRT3, which is an NAD + -dependent deacetylase." (PMID 25902914, 2015). "OA, a natural product from Scutellaria, can upregulate SIRT3 expression and inhibit glycolysis in breast cancer cells under hypoxia through enhancing SIRT3-mediated stabilization and activation of HIF1α." (PMID 25855962, 2015).
breast cancer (continued). "Other than MDA-MB-231 cells, OA also inhibited glycolysis of breast cancer MCF-7 cells under hypoxia via increasing SIRT3, which was increased in the mRNA level as well as in protein level." (PMID 25855962, 2015). "Here, we show that oroxylin A inhibits glycolysis in breast cancer cells via the Sirtuin 3 (SIRT3)-mediated destabilization of hypoxia-inducible factor 1α (HIF1α), which controls glycolytic gene expression." (PMID 25855962, 2015). "Our results indicate that OA is an effective activator/regulator of SIRT3 in breast cancer, providing more extent information for evaluating the role of SIRT3 for cancer therapeutic intervention." (PMID 25855962, 2015). "We show that HNK increases the expression of SIRT1 and SIRT3 and overexpression of SIRT1 and SIRT3 increases the cytoplasmic localization of LKB1 in breast cancer cells." (PMID 26359358, 2015). "Oroxylin A inhibited glycolysis by promoting the SIRT3-mediated deacetylation of cyclophilin D in breast carcinoma." (PMID 25902914, 2015). "Initially identified as a tumor suppressor in breast cancer, SIRT3 maintained the integrity of mitochondria during stress and Hif1α destabilization." (PMID 26317998, 2015). "Adding to the importance of SOD1 in the mitochondria is a recent study from the Haigis' group showing that SIRT3 is either completely lost or reduced in 87% of breast cancers." (PMID 24955214, 2014). "Recently, SIRT3 was reported to be decreased in 87% of breast cancers, resulting therefore in a decrease in the activity of SOD2 and an elevation in ROS." (PMID 24955214, 2014). "Recently, several groups have provided evidence that SIRT3 is required to suppress tumorigenesis, and to induce stress-mediated cell death in tumors, including breast cancer, colorectal carcinoma, osteosarcoma, and leukemia." (PMID 23800187, 2013). "More importantly, the inverse correlation between Skp2 and SIRT3 immunohistochemical staining was observed in breast cancer tissues." (PMID 23230084, 2012). "Elevated mitochondrial oxidative stress was proposed to play a role, at least in part, for the development of breast cancers in humans as well as the development of mammary tumors in the aged Sirt3 knockout mice." (PMID 22016654, 2011). "SIRT3 protein levels are decreased in human breast cancers as well as several other human malignancies suggesting that SIRT3 is a genomically expressed, mitochondrial localized tumor suppressor." (PMID 21386137, 2011). "Therefore, NDUFV1 and SIRT3/7 have emerged as promising therapeutic targets against this breast cancer subtype." (PMID 39873399, 2025). "Notably, patients who achieved pathological complete response exhibited significantly lower SIRT3 expression, with a hazard ratio of 17.98 for survival—highlighting a paradoxical, context-dependent role of SIRT3 in breast cancer." (PMID 41471349, 2025). "This suggests that SIRT3 or PGC-1α may suppress glycolytic metabolism to inhibit breast cancer cell growth." (PMID 40303296, 2025). "In addition, Germain’s group identified the mitochondrial deacetylase SIRT3 axes as a coordinator of the mtUPR in breast cancer." (PMID 40943612, 2025). "For example, SIRT3 suppresses cell proliferation as well as anaerobic glycolysis in breast cancer." (PMID 39501597, 2024). "However, Sirt3 inhibition promotes the ROS-dependent proteasomal degradation of the Mcl-1 and survivin proteins, thereby triggering apoptosis in breast cancer cells." (PMID 39472438, 2024). "SIRT3 might be considered as a potential target for overcoming TMX resistance in treatment of breast cancer." (PMID 37646973, 2023). "Sirt3 overexpression suppresses breast cancer cell proliferation by regressing glycolysis." (PMID 36739437, 2023). "Recent studies have pointed out that SIRT3 is a critical regulator of cell metabolism and played a dual role in cancer, as it can act as a suppressor or promoter in a variety of tumors, such as breast cancer, colon cancer, and prostate cancer." (PMID 37362244, 2023).
breast cancer (continued). "They found that Compound 33c (identified via hit-to-lead optimization starting from VS campaign, see Section 3.3) activates SIRT-3, determines breast cancer cell death by autophagy and reduces cell migration by decreasing ROS production hampering MMP activation." (PMID 36080416, 2022). "Furthermore, SIRT3 is a necessary component of the UPRmt required for breast cancer metastasis to secondary organs, which further enriches our information on the dual role of SIRT3 in the regulation of cancer metastasis." (PMID 35832551, 2022). "Similarly, in human breast cancer, the reduction in the expression of SIRT3 results in upregulation of the HIF-1α target genes." (PMID 35897717, 2022). "Breast cancer patients with low SIRT3 expression have short relapse-free survival." (PMID 35571098, 2022). "The expression of SIRT3 is decreased in human breast cancers." (PMID 36291902, 2022). "Corroborating this, the SIRT3 gene is deleted in breast cancer more than in other cancers." (PMID 36291902, 2022). "Some studies have shown that SIRT3 plays a carcinogenic role in breast cancer." (PMID 35571098, 2022). "The opinions differ among researchers concerning the roles of SIRT3 in breast cancer." (PMID 35571098, 2022). "To date, only one study has shown a possible tumor-promoting effect of SIRT3 in breast cancer." (PMID 36291902, 2022). "Zhang’s team showed that SIRT3 expression was higher in Tam-resistant breast cancer cells." (PMID 35571098, 2022). "SIRT3-null mice could develop mammary tumors after one year; meanwhile, SIRT3 expression levels of breast cancers were decreased in humans." (PMID 36230032, 2022). "In contrast, some studies have shown that SIRT3 plays a role in suppressing breast cancer." (PMID 35571098, 2022). "Higher SIRT3 expression predicted a poorer prognosis in breast cancer patients." (PMID 35571098, 2022). "PGC-1α could suppress glycolytic metabolism by activating SIRT3 to moderate breast cancer cell proliferation." (PMID 35832551, 2022). "SIRT3 deacetylates and inactivates cyclophilin D (CypD) to impact the contact of the lactate metabolic enzyme hexokinase II (HK II) with mitochondria, further inhibiting breast carcinoma glycolysis." (PMID 35832551, 2022). "Considering the role of SIRT3 in regulating ROS homeostasis, studies have shown that SIRT3 is essential in extinguishing Src oxidation and Src/Fak signaling to inhibit cell migration and metastasis in breast cancer cells via ROS adjustment." (PMID 33498743, 2021). "Studies have proposed SIRT3 as a prognostic predictor for breast cancer and ovarian cancer." (PMID 35723384, 2021). "The breast carcinoma cells contain low SIRT3 than the normal MCF10A cells due to UPRmt." (PMID 34717757, 2021). "The SIRT3 arm molecular signature of the UPRmt was recently shown to contribute to breast cancer invasiveness and may be an essential mechanism for cancer cells to adapt to proteotoxic and mitochondrial stress, a process called mitohormesis." (PMID 32825455, 2020). "Thus, Sirt3 should be considered to be a potential therapeutic measure for treating E2-dependent breast cancers." (PMID 32244715, 2020). "Thus, Sirt3 can be considered to reduce tumor-initiating capacity of these cells by attenuating response of the ERα positive breast cancer cells to the E2." (PMID 32244715, 2020). "Moreover, SIRT3 can inhibit breast carcinoma glycolysis through deacetylation and inactivation of cyclophilin D. This further inhibits the binding of the lactate metabolism enzyme hexokinase II (HK II) to mitochondria to obstruct glycolysis." (PMID 32724473, 2020). "For instance, in breast cancer SIRT3 could confer resistance to tamoxifen, a commonly used therapy to block the estrogen receptor in this type of cancer." (PMID 28704962, 2017). "Importantly, activation of the SIRT3 axis of the UPRmt was seen in primary breast cancer patients and high expression, using SOD2 as a marker, was significantly associated with worse disease-free survival." (PMID 28798902, 2017).
breast cancer (continued). "We therefore investigated whether the SIRT3 and CHOP axes of the UPRmt may be linked to the metastatic potential of breast cancer cells." (PMID 28798902, 2017). "The Germain group identified the ERα and SIRT3 axes of the UPRmt in breast cancer cells." (PMID 28470001, 2017). "Similarly, suppression of Sirt3 expression blocked the degradation of COX IV induced by hypoxia in human breast cancer cells." (PMID 27270321, 2016). "SIRT3 was first reported as a tumor suppressor in breast carcinoma." (PMID 26317998, 2015). "For instance, it has been shown that the SIRT3−/− mice develop ER/PR-positive mammary tumors." (PMID 25105144, 2014). "Recently, Finley further found that SIRT3 could mediate metabolic reprogramming in human breast cancer cells by destabilizing HIF1α." (PMID 25103363, 2014). "Following the finding that SIRT3 is decreased in 87% of breast cancer, we hypothesized that decreased expression of SIRT3 may be counterbalanced by an up-regulation of SOD1." (PMID 24955214, 2014). "Strikingly, Sirt3 knockout mice spontaneously develop mammary cancer." (PMID 25085992, 2014). "However, in another study, significant decrease of SIRT3 was observed in 992 human breast cancer samples." (PMID 23272146, 2012). "Moreover, decreased SIRT3 expression has been linked to shorter locoregional survival without relapse in breast cancer." (PMID 37175631, 2023). "Also, elevated Sirt3 mRNA can be found in breast cancer patients with lymph node metastasis." (PMID 36739437, 2023). "The authors further demonstrated that SIRT3 loss reduced IDH2 activities by decreasing IDH2 dimerization and that IDH2 acetylation at lysine 413 impairs mitochondrial respiration and detoxification, increases ROS production, and correlates with Luminal B breast cancer risk." (PMID 36291902, 2022). "Recently, one study deserves attention that SIRT3 may play a protective role in the glucose-deprivation-induced cell death of breast cancer cells by regulating the xCT expression, also known as solute carrier family 7 member 11 (SLC7A11), to balance the ROS levels." (PMID 35832551, 2022). "SIRT3 silencing could produce an increment in ROS production and compromise the antioxidant response, thus, producing an enhancement of cisplatin-triggered apoptosis, which sensitizes breast cancer cells to cisplatin treatments." (PMID 35832551, 2022). "In breast cancer, SIRT3 knockdown could enhance the effect of chemotherapy drugs." (PMID 35832551, 2022). "In addition, 87% of breast cancer decreases the expression of SIRT3." (PMID 32438569, 2020). "For example, in breast cancer, the over-expression of SIRT3 decreases the rate of glycolysis and inhibited cell proliferation followed by tumor suppression, whereas down-regulation of SIRT3 increased ROS production leading to HIF-1α stabilization and upregulation of HIF-1α target genes." (PMID 32252351, 2020). "Thus, we hypothesized that overexpressed Sirt3 indirectly regulates the expression of ERα in MCF-7 breast cancer cells." (PMID 32244715, 2020). "However, the upregulation of SIRT3 could reduce migration and block metastasis in breast cancer cells." (PMID 33193750, 2020). "In addition, SIRT3 may play a protective role in the glucose-deprivation-increased ROS levels and glucose-deprivation-induced cell death of breast cancer cells with a high expression of xCT." (PMID 32630312, 2020). "To examine whether the function of xCT is also essential for the glucose-deprivation-increased ROS levels and glucose-deprivation-induced cell death of the breast cancer cells with an SIRT3 knockdown, we treated the SIRT3 knockdown cells with the xCT inhibitor SSA." (PMID 32630312, 2020). "Some reports suggest that SIRT3 could have a crucial role in the development and progression of some types of cancer acting as a tumour promoter, such as breast cancer, colon cancer, gastric cancer, esophageal cancer, oral squamous cell carcinoma, melanoma, and renal cancer." (PMID 28704962, 2017).
breast cancer (continued). "In addition, reduced expression of SIRT3 was observed in human breast cancer." (PMID 27483432, 2016). "Thus, ERα and ERβ appear to differentially regulate SIRT1, consistent with a yin-yang action pattern in tissues where both isoforms are co-expressed and with a recent study showing that SIRT3 protein levels are affected by the ERα/ERβ ratio in breast cancer specimens." (PMID 23734259, 2013). "SIRT3 regulated IDH2 dimerization by mediating Lys413 site acetylation of IDH2, which regulated the metabolism and progression of breast cancer." (PMID 40421455, 2025). "SIRT3 deacetylated the Lys228 site of pyrroline-5-carboxylate reductase 1 (PYCR1) to regulate the metabolism of proline, which promoted the development of breast cancer." (PMID 40421455, 2025). "MHY2256 has been shown to reduce breast cancer cell viability in preclinical studies by downregulating the expression of SIRT1, SIRT2, and SIRT3." (PMID 41304967, 2025). "The suggested Sirt3 activator ADTL-SA1215 possesses high potency and is effective in cell and mouse models of breast cancer." (PMID 38474697, 2024). "For instance, SIRT3 can repress the activity of HK2 and deacetylate PDC in gastric and breast cancers." (PMID 37175631, 2023). "Compound 33c (ADTL-SA1215) may be the earliest SIRT3-specific small molecule activator in the current research field, which can regulate the SIRT3-driven autophagy/mitophagy signaling pathways to inhibit the proliferation and invasion of human breast cancer cells." (PMID 35832551, 2022). "Further, SIRT3 expression also induced the formation of multinucleated cells and apoptosis and inhibited the proliferation of MDA-MB-231 breast cancer cells." (PMID 36291902, 2022). "Despite the negative regulation of glycolysis by SIRT6, SIRT3 and SIRT5 were found to contribute to cancer cell proliferation and survival in diffuse large B cell lymphoma and breast cancer by regulating the function of metabolic enzymes." (PMID 35897717, 2022). "Upregulated sirtuin 3 (SIRT3) was confirmed to inhibit the acetylation degree and PPIase activity of CypD and lead to the separation of CypD from ANT in breast cancer cells treated with oroxylin A." (PMID 35860554, 2022). "Supporting this finding, a recent study demonstrated that the overexpression of SIRT3 promoted apoptosis and inhibited the proliferation of MCF-7 and MDA-MB-231 breast cancer cells." (PMID 36291902, 2022). "Sirt3 activation by the small-molecule compound 33c (ADTL-SA1215) induced mitophagy and inhibited proliferation and migration in human breast carcinoma cells." (PMID 35938164, 2022). "Conversely, SIRT3 opposes the Warburg effect via the destabilization of HIF1A, preventing cancer proliferation in glycolytic malignancies, such as breast cancer, acting as a tumor suppressor." (PMID 34831420, 2021). "Mitochondrial nicotinamide adenine dinucleotide-dependent deacetylase, Sirtuin-3 (Sirt 3) defect downregulates mtDNA repair gene (8-oxoguanine DNA glycosylase, OGG1-2a), increasing the proliferation of oral cancer, breast cancer, head and neck carcinoma." (PMID 34717757, 2021). "In addition, SIRT3 might play a protective role in the glucose-deprivation-increased ROS levels, in particular mtROS, and in the glucose-deprivation-induced cell death of breast cancer cells with a high expression of xCT." (PMID 32630312, 2020). "In MCF7 and MDA-MB-231 breast cancer cell lines, RES decreased breast cancer cell mass and viability in a dose-dependent manner, concomitantly with an increase in SIRT1 and SIRT3 protein content." (PMID 31159437, 2019).